TLR4 (toll like receptor 4)
Diseases named in the same sentence as TLR4 in open-access papers (continued):
Sharing a sentence is not in itself a finding about the gene and the disease.
tumor (continued). "TLR4 on the surface of macrophages interacts with CCRL2 to promote anti-tumor T cell immunity by enhancing TLR4-mediated immune-stimulated macrophage activation." (PMID 39600941, 2024). "CD11c high tumor-infiltrating DCs displayed a “semi-mature” phenotype when stimulated by TLR4, and they only partially matured and secreted limited amounts of cytokines, indicating a poor antigen-presenting cell function." (PMID 39238498, 2024). "Bacterial stimulation of TLR4 on innate immune cells initiates inflammation, promoting tumor growth." (PMID 38930793, 2024). "Various studies have reported that certain regulatory factors mediate the protective function of anti-tumor immunity through TLR4 in DCs." (PMID 39238498, 2024). "Some studies shown that TLR4 activation in tumor cells can upregulate the expression of PD-L1 and contribute to tumor immune escape." (PMID 38612546, 2024). "Tumor cell-released autophagosomes (TRAPs) can convert macrophages into an M2-like phenotype via the TLR4/MyD88/p38/STAT3 pathway, subsequently suppressing T cell activation." (PMID 39430253, 2024). "It balances tumor cell apoptosis and autophagy via the TLR4/MyD88 signaling pathway, promoting chemoresistance to 5-fluorouracil and oxaliplatin." (PMID 39545038, 2024). "TLR4 activation on immune cells, such as dendritic cells, can enhance anti-tumor immunity by promoting the expression of pro-inflammatory mediators and cytokines like IFN-γ." (PMID 38903515, 2024). "For instance, an attenuated Salmonella typhimurium strain engineered to secrete Vibrio vulnificus flagellin B (FlaB) in tumor tissues can activate both TLR4 and TLR5." (PMID 38523155, 2024). "Colorectal cancer was induced in male BALB/c mice and then was treated with a 30 mg/kg/day oral dose of RA for a week, and it was found to suppress tumor progression in mice through the inhibition of TLR4-mediated NF-κB and STAT3 activation." (PMID 39057035, 2024). "Lipopolysaccharide (LPS) binds to the TLR4 on tumor cell surface for activating NF-KB pathway to regulate tumor cell invasion and migration." (PMID 38549127, 2024). "TLR-4 activated by lipopolysaccharide (LPS) can promote tumor growth and metastasis in colorectal, gastric, and pancreatic cancer." (PMID 39335585, 2024). "Literature data indicate that increased expression of TLRs, particularly TLR2, TLR4, and TLR9, in tumor cells and the tumor microenvironment is associated with GC progression." (PMID 39451226, 2024). "TLR4/MyD88 stimulation by Fusobacterium nucleatum (F. nucleatum) promotes tumor development via NF-κB activation in CRC." (PMID 39926112, 2024). "Briefly, enhancement of cancer cell proliferation, establishment of a tumor‐promoting immune environment through miRNA‐mediated activation of TLR2/TLR4, and the evasion of immune checkpoints have been proposed as its main mechanisms." (PMID 38102837, 2024). "Five studies observed the relationship between TLR4 expression and tumor size, and we selected the fixed-effect model for analysis." (PMID 38463226, 2024). "We found that TLR4, together with HIF-1α and PD-L1, was negatively expressed in adjacent normal tissue but positively expressed in tumor tissue, implying a positive correlation between TLR4 and HIF-1α/PD-L1." (PMID 38612546, 2024). "The CXCR7/CXC12 axis, known for promoting angiogenesis and cell invasion, is associated with CRC cell proliferation and migration, highlighting TLR4’s role in modulating tumor cell behavior through chemokine signaling pathways." (PMID 38930793, 2024). "One study’s findings include the significant downregulation of SOCS3 in DRG following tumor cell injection, and subsequent overexpression attenuated pain hypersensitivity probably via reversing TLR4 upregulation." (PMID 38940936, 2024).
tumor (continued). "TLR4 signaling exacerbates this inflammatory milieu within the tumor microenvironment by stimulating the production of pro-inflammatory cytokines and chemokines, thereby fostering tumor growth and metastasis." (PMID 38903515, 2024). "LPS can stimulate tumor cell progression by activating Toll-like receptor 4 (TLR4) through IL-6, which can subsequently induce phosphatidylinositol-3 kinase (PI3K) activation and epithelial–mesenchymal transition (EMT)." (PMID 39497925, 2024). "Further studies on larger series are needed to better understand the role of TLR4 in tumor evasion from the immune surveillance and to individuate anti-TLR4 vaccines." (PMID 39451550, 2024). "In a CRC xenograft model, Xiaochai Hu Decoction suppresses tumor progression via gut microbiota modulation, implicating the TLR4/MyD88/NF-κB pathway." (PMID 38930793, 2024). "In mouse models of metastatic CRC, NET-derived neutrophil elastase activates TLR4 signaling on tumor cells, enhancing mitochondrial ATP production, and subsequently promoting primary tumor growth." (PMID 39795864, 2024). "Another study showed that F. nucleatum activates TLR-4, which ultimately results in s1000A9 expression and M2 macrophage polarization to help tumor cells achieve immune evasion." (PMID 39624362, 2024). "Clostridium nucleatum (Fn)-induced NETs promote tumor metastasis through the Toll-like receptor 4 (TLR4)-reactive oxygen species (ROS) signaling pathway and the NOD-like receptor (NOD1/2)-dependent signaling pathway." (PMID 39100676, 2024). "In healthy appearing tissue samples from OSCC patients with candidal colonization at the tumor site, the staining intensity of TLR4 was significantly increased at the BM zone when compared to OSCC samples with no Candida (P = 0.01)." (PMID 38593176, 2024). "Meanwhile, curcumin suppressed tumor immune escape by inhibiting the TLR4/HIF-1α/PD-L1 pathway in the inflammatory environment of CRC." (PMID 38612546, 2024). "HMGB1, which binds to TLR4, aids in tumor-antigen processing and presentation, enhancing the anti-tumor immune response through its effect on DCs." (PMID 39456655, 2024). "In our study, we discovered that tumor cells exploit FN-EDA to induce the expression of SHMT1 via the TLR4/NF-κB pathway." (PMID 39286657, 2024). "TLR4 is crucial for dendritic cell activation and enhancing anti-tumor T cell responses through DAMPs released by cancer cells under stress conditions." (PMID 38930793, 2024). "The upregulation of TLR4 in HCC cells activates the STAT3 signalling pathway which promotes tumour progression, aggressiveness, and chemoresistance, thereby conferring poor patient prognosis." (PMID 39684877, 2024). "Meanwhile, butyrate can enhance nuclear factor kappa B (NF‐κB) signalling activation mediated by Toll‐like receptor 4 (TLR4) in colon cancer cells, thereby strengthening anti‐tumour innate immunity." (PMID 39568157, 2024). "Anti-tumour vaccination efficacy of doxorubicin or oxaliplatin-treated MCA205 sarcoma cells in mice that were TLR4-/- was reduced compared to wild-type mice." (PMID 38353760, 2024). "Toll-like Receptor4 (TLR4) plays an essential role in the immune surveillance of tumor cells, and it has been shown that CAV1 is involved in the regulation of TLR431-33." (PMID 39494337, 2024). "TLR4 expression levels were shown to be substantially connected with tumor size, cell migration, local lymphatic metastasis, histopathological grade, and tumor stage, and they were shown to be higher in BC tissues than in normal breast tissues." (PMID 38685971, 2024). "When TLR4 enhances inflammatory and anti-apoptotic signals, the key transcription factor involved is NF-κB, leading to adverse effects such as tumor formation." (PMID 39529796, 2024). "expected that targeting TLR4 would convert M2 macrophages to M1 macrophages and alter the tumor microenvironment (TME) to achieve therapeutic effects on tumors." (PMID 38685971, 2024).
tumor (continued). "The administration of exogenous Ficolin-2 was observed to effectively inhibit tumor cell growth in murine tumor models by binding to TLR4 in DCs and enhancing their antigen-presenting abilities to CD8+ T cells." (PMID 39238498, 2024). "Tumor-derived Tenascin-C facilitates immunosuppression and promotes pro-tumor (M2) macrophage phenotype via activation of macrophage toll-like receptor-4 (TLR-4) through the binding of the TNC protein C-terminal Fibrinogen-like globe (FBG) domain." (PMID 39660126, 2024). "The TLR4 axis can regulate tumor growth and metastasis by enhancing the immunosuppressive function of MDSCs." (PMID 38313314, 2024). "Although the study of the specific role of TLR4 is outside the scope of the current study, determining the significance of TLR4 levels and the conflicting roles in tumor progression opens up an interesting avenue for further investigation." (PMID 39768151, 2024). "The hyperthermia-induced elements are crucial because they are responsible for initiating tumor-specific immune responses, mainly by activating Toll-like receptor-4 (TLR-4) signaling pathways." (PMID 39512770, 2024). "Perivascular macrophages, activated via TNC and TLR4 to induce the formation of pro-tumor vascular niche that drives tumor metastasis." (PMID 38580870, 2024). "TLR4 is known to promote metastasis in various cancers by influencing the EMT process, and its interaction with MyD88 is linked to increased tumor development and progression in intestinal tumorigenesis." (PMID 39390599, 2024). "Future in vivo studies are warranted to explore its efficacy in cancer therapy, and its ability to activate TLR4 downstream pathways and inhibit tumor cell adhesion." (PMID 38930793, 2024). "This is because exogenous CaNB can quickly enter cells through TLR4 receptors and generate cytotoxicity in some TLR4-rich tumor cells." (PMID 39640496, 2024). "In summary, we demonstrate a connection between TGF-β, IL-6, TLR-2 and TLR-4 expression by the primary CRC tumor to SPP1 and FN1 expression in the metastatic intrahepatic tumor." (PMID 39372792, 2024). "Upon detecting tumor antigens, TLR4 triggers the activation of MyD88 (myeloid differentiation factor 88), which in turn initiates the translocation of NF-κB to the nucleus, followed by the transcription of target genes." (PMID 39390599, 2024). "Activation of dendritic cells by TLR4 plays an important role in enhancing anti-tumor T cell immune response." (PMID 39600941, 2024). "TLR4 signaling on IECs is crucial for recruiting and activating macrophages, influencing the tumor microenvironment, and promoting dysplastic lesions in CRC." (PMID 38930793, 2024). "Immunogenic cell death inducers trigger release of HMGB1, which by binding to TLR4, promotes the processing and presentation of tumor antigens by inhibiting their premature lysosomal degradation." (PMID 39417004, 2024). "In specific scenarios, TLR4 triggers anti-tumor immune responses by activating dendritic cells and cytotoxic T lymphocytes." (PMID 38903515, 2024). "Interestingly, the authors find that the anti-tumor effect of Tasquinimod is conserved in TLR4-deficient mice, indicating that Tasquinimod effect might be due to blocking S100A9-signaling through other receptors, or potentially to additional, yet unidentified mechanisms." (PMID 39497822, 2024). "Toll-like receptor 4 (TLR4) expression protects HNSCC tumor cells from NK cell-induced immune attack through the antiapoptotic properties of activated NF-κB." (PMID 38398094, 2024). "Altogether, SNLP‐1 can enhance immune activity and play an anti‐tumor role by regulating the TLR4‐mediated MyD88‐dependent signaling pathway." (PMID 39155844, 2024). "In CAC, dihydroartemisinin inhibits tumor growth by targeting the TLR4 pathway, enhancing cell cycle arrest and apoptosis." (PMID 38930793, 2024).
tumor (continued). "They potentially inhibit spermine oxidase expression, demonstrating anti-inflammatory properties and modulation of the TLR4/NF-κB pathway, vital for future anti-tumor research." (PMID 38930793, 2024). "This personalized vaccine can enhance the phagocytosis of autologous tumor antigens by dendritic cells (DCs) and facilitate DCs maturation through TLR4, and build an efficient immune protection to prolong the survival while maintaining good biocompatibility." (PMID 38353384, 2024). "The use of lipopolysaccharide (LPS) in the LM8 cell line to activate TLR-4 resulted in the discovery of more CD8+ T cells in the tumor metastases and the suppression of tumor volume in the primary foci." (PMID 39916962, 2024). "Taken together, these findings confirmed the significant immunoadjuvant role of HMGB1 release from dying tumour cells and its interaction with associated PRR TLR4 on APCs as part of ICD." (PMID 38353760, 2024). "IAA inhibits tumor progression by activating the Toll-like receptor 4 (TLR4)-c-Jun N-terminal kinase (JNK) pathway in CRC." (PMID 38462620, 2024). "On the other hand, we, and others, have shown that TLR4-mediated chronic inflammation can lead to tumor progression in a mouse model of ultraviolet (UV) B-mediated carcinogenesis." (PMID 39684439, 2024). "The expression of TLR4 also gives rise to tumor progression, driving the activation of signaling pathways leading to the production of mitogen-associated protein kinases (MAPKs), nuclear factor (NF)-κB, and inflammatory cytokines." (PMID 39451550, 2024). "The introduction of G‐EVLPs can enhance the phagocytosis of autologous tumor antigens by dendritic cells (DCs) and facilitate DCs maturation through TLR4, ultimately activating tumor‐specific cytotoxic T lymphocytes (CTLs)." (PMID 38353384, 2024). "Nevertheless, this cytokine, through the IL-10/STAT3 or TLR4/IL-10 signaling pathways, promotes the formation of M2 macrophages and activates the expression of the genes responsible for anti-apoptotic, pro-tumor and immunosuppressive activity." (PMID 39057050, 2024). "The results of our study confirm that HLA-A and TLR4 act as tumor suppressor genes during tumorigenesis and tumor progression." (PMID 36969077, 2023). "In fact, inflammatory cytokines, chemokines, and several other growth factors generated through the signaling cascade originating through the TLR4-MyD88-NF-κB axis regulate tumor growth as well as infiltration of the immune cells." (PMID 37822929, 2023). "Relevant to this point, our data show for the first time that PTX3 exerts its pro-tumor activity in TNBC by activating TLR4/IRAK1/NF-kB signaling in tumor cells." (PMID 37749607, 2023). "A link between increased TLR4 expression and the severity of cervical lesions was found and was closely associated with FIGO stage, lymph node metastases, and tumor size in CC." (PMID 37370894, 2023). "Mechanistically, ETBF can migrate from the intestinal tract and localize to the mammary gland, where it induces epithelial cell proliferation and promotes tumor growth and metastasis in a Toll-like receptor 4 (TLR4)-dependent pathway." (PMID 37828613, 2023). "Meanwhile, paclitaxel can promote tumor regression via TLR4/NF-κB signaling in melanoma by inducing M1 macrophage polarization." (PMID 37701037, 2023). "Fusobacterium simultaneously triggers the IL-6/p-STAT3/c-MYC signaling pathway and encourages M2-type differentiation of macrophages through a TLR4-dependent mechanism, promoting tumor growth." (PMID 36845103, 2023). "Specifically, they used antibiotics in rats or the genetic ablation of TLR4 in mice to reduce LPS levels, which prevented excessive tumor growth and multiplicity." (PMID 37896221, 2023). "The TLR4 pathway can activate platelets in response to high-mobility group box1 (HMGB1) released from dying tumor cells destroyed by NK cells and shear stress." (PMID 36937386, 2023).
tumor (continued). "These genes included those related to P/DAMP signaling (e.g., Il6, Tlr1, Tlr4, Il1b, Il18), necroptotic tumor cell death (e.g., Casp1, Casp8, Il1b), and activation of the adaptive immune system (e.g., Cd80, Cd8a, Ccr5, Cxcl10)." (PMID 37213298, 2023). "Our results have clearly suggested that the activation of TLR4 noticeably retained mice from aggressive tumor progression and improved the survival time of the tumor-bearing mice." (PMID 37553698, 2023). "The results revealed that the expression of CLEC12A was higher in ALDH+ population of Tumor, TLR4 was higher in ALDH+ population of T+25." (PMID 38144525, 2023). "Cucurbitacin B (CuB), a compound extracted from muskmelon pedicel, inhibits tumor growth in NSCLC cells by directly binding to TLR4, activating the NLRP3 inflammasome and inducing pyroptosis." (PMID 37752941, 2023). "Our results suggested that KD enhances tumor inflammation partly due to IL-17, TLR4, and NF-κB p65 activation." (PMID 37239383, 2023). "Mechanistically, NETs-associated protein, NE, directly act TLR-4 on the cancer cells, leading to activation of the p38-PGC-1α pathway, followed by increased tumor mitochondrial function and increased tumor growth." (PMID 36993957, 2023). "The inhibition of TLR4 signaling in macrophages reduced the number and activity of Tregs and slowed tumor growth in mice with HCC." (PMID 37345131, 2023). "Proinflammatory CD80, anti‐inflammatory CD206, CCL18, and CCL22, and the tumor‐associated markers including MMPs, MGLL, and TLR4 were expressed by a low proportion of monocytes (<1%), but significantly upregulated in TAM." (PMID 38037545, 2023). "PD-L1 is an immunosuppressive molecule produced in response to TLR-4/MyD88 signaling cascade, which favors immune escape in tumor cells; its blockade has a positive impact in decreasing PDAC growth when associated with LPS reduction." (PMID 36838231, 2023). "In particular, the authors found that Tim-3, in addition to being expressed on the cell types previously considered, can also be expressed on endothelial cells after stimulation with Toll-Like Receptor 4 (TLR4) ligand released by tumour cells." (PMID 36980583, 2023). "Collectively, our results suggest that F. nucleatum plays an important role in BC tumor growth and metastasis by regulating TLR4 through Fn-EVs." (PMID 37221488, 2023). "The present study revealed that ME had a repressive response to TLR4 using a chemical carcinogenesis model, and its inhibition suggested that TLR4-mediated NF-κB exerted an effect on tumor burden reduction." (PMID 37200915, 2023). "Instead, TLR4 is stimulated through the binding of LPS over the tumor cells to increase the production of inflammatory cytokines that lead to inhibiting the ability of CTLs for cancer cell recognition and death." (PMID 37822929, 2023). "HMGB1 secreted by tumor cells binds to various PRRs (e.g., Toll-like receptor 4 (TLR4)) and promotes the release of cytokines such as IL-1b." (PMID 37275861, 2023). "It was further investigated that NETs enhanced the invasion capacity of trapped tumor cells through the activation of the TLR4/9 receptor and the phosphorylation of P65 and cyclooxygenase-2 (COX2) overexpression." (PMID 36859358, 2023). "TLR4 can also induce angiogenesis, the formation of new blood vessels, which is important for tumor growth and spread." (PMID 36864611, 2023). "LPS demonstrates the ability to activate TLR4 signaling in tumor cells, aiding these cells in evading attacks from cytotoxic lymphocytes and natural killer cells." (PMID 38067244, 2023). "TLR-4 also promotes the polarization of M2 macrophages (alternatively activated), which is related to tumor relapse after chemotherapy, lymphatic metastasis and a poor prognosis in CRC." (PMID 36838231, 2023). "Our recent report demonstrated that CXCL10, the increased inflammatory cytokine resulted from liver graft injury, recruited MDSCs into liver graft through TLR4/MMP9 to promote tumor recurrence post transplantation." (PMID 37175922, 2023).